IFITM3 (interferon induced transmembrane protein 3)
Description:
IFN-induced antiviral protein which disrupts intracellular cholesterol homeostasis. Inhibits the entry of viruses to the host cell cytoplasm by preventing viral fusion with cholesterol depleted endosomes. May inactivate new enveloped viruses which buds out of the infected cell, by letting them go out with a cholesterol depleted membrane. Active against multiple viruses, including influenza A virus, SARS coronaviruses (SARS-CoV and SARS-CoV-2), Marburg virus (MARV), Ebola virus (EBOV), Dengue virus (DNV), West Nile virus (WNV), human immunodeficiency virus type 1 (HIV-1), hepatitis C virus (HCV) and vesicular stomatitis virus (VSV). Can inhibit: influenza virus hemagglutinin protein-mediated viral entry, MARV and EBOV GP1,2-mediated viral entry, SARS-CoV and SARS-CoV-2 S protein-mediated viral entry and VSV G protein-mediated viral entry. Plays a critical role in the structural stability and function of vacuolar ATPase (v-ATPase). Establishes physical contact with the v-ATPase of endosomes which is critical for proper clathrin localization and is also required for the function of the v-ATPase to lower the pH in phagocytic endosomes thus establishing an antiviral state. In hepatocytes, IFITM proteins act in a coordinated manner to restrict HCV infection by targeting the endocytosed HCV virion for lysosomal degradation. IFITM2 and IFITM3 display anti-HCV activity that may complement the anti-HCV activity of IFITM1 by inhibiting the late stages of HCV entry, possibly in a coordinated manner by trapping the virion in the endosomal pathway and targeting it for degradation at the lysosome. Exerts opposing activities on SARS-CoV-2, including amphipathicity-dependent restriction of virus at endosomes and amphipathicity-independent enhancement of infection at the plasma membrane.
Synonyms: DSPA2b; 1-8U; IP15
Tractability: Antibody: UniProt places it where antibodies can reach, with high confidence; its Gene Ontology location is reachable by antibodies, with high confidence; UniProt predicts a signal peptide or a membrane-spanning region. PROTAC: UniProt records ubiquitination sites on it; ubiquitination databases record sites on it.
Gene: Protein-coding gene on chromosome 11 (319,675 to 329,475, reverse strand). Ensembl gene ENSG00000142089.
Subcellular location: Cell membrane; Late endosome membrane; Early endosome membrane; Lysosome membrane; Cytoplasm, perinuclear region
Pathways (Reactome):
Immune System: Interferon alpha/beta signaling
Gene Ontology:
Molecular function: protein binding
Biological process: defense response to virus; host-mediated suppression of symbiont invasion; negative regulation of viral genome replication; negative regulation of viral transcription; response to interferon-alpha; response to interferon-beta; response to type II interferon; response to virus; immune response; type I interferon-mediated signaling pathway
Cellular component: early endosome membrane; late endosome membrane; lysosomal membrane; plasma membrane; protein-containing complex; membrane; perinuclear region of cytoplasm
Genetic constraint (gnomAD): Loss-of-function variants: 5 observed, 5.94 expected, observed/expected ratio (o/e) 0.84, 90% interval 0.44 to 1.67. That is too few expected variants to judge how well the gene tolerates losing a copy. Missense variants: 156 observed, 178.04 expected, observed/expected ratio (o/e) 0.88, 90% interval 0.77 to 1. Synonymous variants: 81 observed, 75.85 expected, observed/expected ratio (o/e) 1.07, 90% interval 0.89 to 1.28.
Homologues: Orthologues: mouse Ifitm3 (67% identical), mouse Ifitm2 (65% identical), rat Ifitm3-ps2 (62% identical), mouse Ifitm7 (53% identical), mouse Ifitm1 (53% identical), rat Ifitm1 (53% identical). Paralogues in human: IFITM2 (90% identical), IFITM1 (66% identical), IFITM10 (35% identical), IFITM5 (30% identical).
Diseases named in the same sentence as IFITM3 in open-access papers:
IFITM3 is named in the same sentence as 158 diseases in open-access papers, as found by Europe PMC text mining. Sharing a sentence is not in itself a finding about the gene and the disease. The quoted sentences say what the papers report.
viral infection (162 papers, 2010 to 2026). "Following infection with influenza or SARS-CoV-2, MKs express a higher level of the IFITM3 gene, which encodes for interferon-induced transmembrane protein 3 and plays critical role in host immunity against viral infections." (PMID 40710306, 2025). "Functionally, MARCH8 expression attenuated the IFITM3-mediated restriction of vesicular stomatitis virus and influenza A virus entry, thereby increasing cell susceptibility to viral infection." (PMID 41197719, 2025). "Review of the literature indicates that IFITM3 SNPs are primarily associated with increased viral disease in infections with emergent influenza viruses, such as the 2009 H1N1 pandemic virus and zoonotic H7N9 virus." (PMID 40237465, 2025). "Studies in IFITM3-deficient mice further support an essential role of IFITM3 in restricting viral infection and reducing disease severity." (PMID 40237465, 2025). "In this study, we discovered that MARCH8 ubiquitinates an IFN-stimulated gene product IFITM3, this provides a mechanism of regulating IFITM3 expression and potentially renders cells more susceptible to viral infection." (PMID 41197719, 2025). "These two regulatory SNPs affected the transcriptional activity of the IFITM3 gene and were linked to the severity and susceptibility of viral infections including COVID-19 infection and IAV." (PMID 37323564, 2023). "Due to the importance of IFITM3 in viral infection, its polymorphism is critical for an adapted response of the innate immune system to viral infections." (PMID 36992298, 2023). "Genetic polymorphisms within the IFITM3 locus have been linked to increased pathogenesis of viral infections such as IAV and SARS-CoV-213,14." (PMID 36075894, 2022). "Two SNPs of IFITM3, rs12252-C, and rs34481144-A were reported to be associated with the disease severity of several virus infections." (PMID 36423162, 2022). "These two regulatory SNPs impacted the IFITM3 gene transcriptional activity and were associated with the severity and susceptibility to viral infection such as COVID-19 infection and influenza A virus." (PMID 36403064, 2022). "The abnormality of the IFITM3 gene in vivo is involved in severe clinical symptoms caused by pathogenic viral infection." (PMID 35769480, 2022). "The rs12252 C allele of IFITM3 has been reported to be associated with the disease severity of several viral infections, including influenza virus, Hantaan virus, and HIV-1." (PMID 36423162, 2022). "Further studies found that the IFITM3 single nucleotide polymorphism (SNP) rs12252 correlated with the severity of disease caused by viral infection." (PMID 36325336, 2022). "In conclusion, the IFITM3 rs12252-C allele is strongly associated with the severity of some viral infectious diseases." (PMID 36325336, 2022). "In humans, the SNP rs12252-C allele of IFITM3 was linked to severe illness in adults during H1N1/09 virus infections, as well as following infection with the novel H7N9 virus." (PMID 32321380, 2020). "The SNP rs12252-C allele of IFITM3 had been linked with severe illness in adults during pandemic influenza H1N1/09 virus infections, but the mechanisms remain incompletely understood." (PMID 32321380, 2020). "Tissue resident memory T cells in the airways, lung, skin and brain constitutively express IFITM3, and this is associated with enhanced resistance to viral infection and therefore long-term survival within peripheral tissues." (PMID 30650117, 2019). "Fourth, IFITM3 knockout mice experience increased susceptibility to a wide range of virus infections." (PMID 30662816, 2018). "The antiviral restriction factor IFN-induced transmembrane protein 3 (IFITM3) inhibits cell entry of a number of viruses, and genetic diversity within IFITM3 determines susceptibility to viral disease in humans." (PMID 28240600, 2017).
viral infection (continued). "IFITM3 induction was assessed in response to the dsRNA analogue poly(I : C), a molecular pattern associated with viral infection, which is recognized by Toll-like receptor 3 and induces type I IFN in porcine and bat cells." (PMID 25614588, 2015). "Another striking example is derived from the IFITM3 which encodes for an antiviral protein that inhibits viral infection of the host and its TSS-proximal sequences encompass rs35218683 that is linked to MS, resides adjacent to the SHAe that lies within/vastly proximal to the pmSE of the gene." (PMID 40131776, 2025). "Moreover, Ifitm3 knockout mice and disease-associated single-nucleotide polymorphisms in human IFITM3 revealed that IFITM3 prevents severe viral disease sequelae in vivo." (PMID 39653855, 2025). "Increased fetal survival during certain infections in the absence of IFITM3 thus represents the prevailing theory for how IFITM3 deficiencies may provide a selective benefit despite increasing susceptibility to emergent virus infections later in life." (PMID 39477971, 2024). "Thus, the role of IFITM3 in suppressing viral infection is thought to be critically linked to the lysosome, and lysosome acidification and protease activity have been identified in association with some viral infections." (PMID 37239983, 2023). "Given that the genetic removal of NDFIP2 in A549 cells resulted in a decrease in the steady-state levels of IFITM3, we sought to determine whether this translated into a higher susceptibility of these cells to viral infection." (PMID 37896772, 2023). "As such, NDFIP2 levels may represent a fine-tuning step in the regulation of the steady-state levels of IFITM3, leading to dynamic changes in the cell susceptibility to viral infection." (PMID 37896772, 2023). "Polymorphisms in IFITM3 have been reported to modulate antibody responses to virus infection." (PMID 36423162, 2022). "In case of inhibitors of IFITM3 activity, the susceptibility to viral infection can increase." (PMID 36153346, 2022). "Similarly, in mouse models of viral infection, Ifitm3 deficiency alters cytokine and chemokine profiles and leucocyte influx to sites of infection." (PMID 36075894, 2022). "This article may help elucidate how IFITM3 restricts virus replication and thus aid in developing novel therapeutic approaches to enhance the immune response against pathogenic virus infection." (PMID 35769480, 2022). "In support of this, mice deficient for IFITM3 are more susceptible to viral infection." (PMID 33567283, 2021). "Further, we analyze and summarize the published literature examining phenotypes of IFITM3 knockout mice upon infections with viral pathogens and discuss the controversial association between single nucleotide polymorphisms (SNPs) in the human IFITM3 gene and severe virus infections." (PMID 30662816, 2018). "Furthermore, the single-nucleotide polymorphism of IFITM3 gene resulted in decreasing IFITM3 protein expression, which has been linked with a higher risk of virus infections." (PMID 29088728, 2017). "Recent data suggest that human polymorphisms in genes that restrict virus infection (e.g., IFITM3 gene) may also play an important role in outcome." (PMID 23441208, 2013). "Thus, IFITM3 may play a significant role in enhancing the persistence of immune cells at mucosal locations, and IFITM3 functional variations may contribute to viral infection risk and illness severity." (PMID 37323564, 2023). "Therefore, the regulation of expression of IFITM3 as an intrinsic host defense factor that are often induced by virus infection, might also be associated with vaccinia virus." (PMID 29503647, 2018). "Thus, it will be interesting and important to determine whether clinical use of amphotericin B has the unintended consequence of increasing susceptibility to or pathogenicity of these and other virus infections due to its neutralizing effects on IFITM3." (PMID 30662816, 2018).
viral infection (continued). "One of the viral restriction factors potentially modulated by viral infection is IFITM3, a factor that functions at the convergence between megakaryocyte differentiation and antiviral responses, including responses against HIV-1." (PMID 39354676, 2025). "The IL-6, ZAP, and IFITM3 expression levels induced by MDV-dUS3 were also remarkably higher than that induced by wild-type virus infection." (PMID 40042340, 2025). "Although the role of IFITM3 in certain viral infections is known, the mechanism of autophagy regulation by IFITM3 in HCT-8 cells infected with C. parvum is unclear." (PMID 40681213, 2025). "TUSC5 and IFITM3 regulate vesicular trafficking during glucose transport and virus infection, respectively, through incompletely understood mechanisms." (PMID 39653855, 2025). "Upregulation of the Stat1-mediated response to the virus, interferon response, immune system activation, and ISGs, such as Rsad2, IFITM3, Cxcl9, Bst2, and Oas2, across all strains confirmed ongoing viral infection." (PMID 39875898, 2025). "Post-translational modifications, including phosphorylation and palmitoylation, regulate IFITM3 localization and antiviral activity, fine-tuning its ability to restrict viral infection (7, 17, –, 19, 33)." (PMID 40237465, 2025). "For example, overexpression of interferon-induced transmembrane protein 3 (IFITM3) in human MKs was found to be significant in limiting viral infection." (PMID 40710306, 2025). "To investigate the relationship between IFITM3 siRNA and AmB in Huh7 cells, we treated the cells with IFITM3 siRNA and AmB either individually or in combination before virus infection." (PMID 40464579, 2025). "One family of ISGs is the IFN-induced transmembrane proteins (IFITMs), including IFITM1, IFITM2, and IFITM3, which limits the viral infection by various viruses." (PMID 41465488, 2025). "This is supported by the recent report showing that IFITM3 is effective in restricting the lower threshold of virus infection." (PMID 40871241, 2025). "Upregulation of the Stat1-mediated response to the virus, interferon response, immune system activation, and interferon-stimulated genes (ISGs; e.g., Rsad2, IFITM3, Cxcl9, Bst2, and Oas2) across all strains confirmed ongoing viral infection." (PMID 39875898, 2025). "Following viral transduction, coexpression of MARCH8 with IFITM3 WT reduced IFITM3 protein levels, correlating with enhanced viral infection efficiency." (PMID 41197719, 2025). "Interferon-induced transmembrane protein 3 (IFITM3) is a cellular protein that restricts numerous viral infections by blocking virus–host membrane fusion." (PMID 40237465, 2025). "The interferon induced transmembrane protein 3 (IFITM3) is a transmembrane protein with multiple functions, including roles in viral infection, Alzheimer’s disease, and cancer." (PMID 41425573, 2025). "IFITM3 plays a crucial role in the innate response against viral infections by hampering viral fusion and endocytosis." (PMID 39354676, 2025). "Taken together, these findings suggest that IFITM3 KO mice have functional immune responses following live virus infection that are protective against subsequent homologous or heterosubtypic virus challenges." (PMID 40501891, 2025). "IFITM3 is an important effector of the innate immune system and plays an important role in host resistance to viral infections." (PMID 38543696, 2024). "In support of viral infection results in IFITM KO mice, multiple studies have shown that single nucleotide polymorphisms (SNPs) in IFITM3 are associated with the severity of IAV and SARS-CoV-2 infections." (PMID 38793616, 2024). "TET2 is a DNA dioxygenase that demethylates the IFITM3 promoter during viral infection, inhibiting HIV Env trafficking and reducing viral spread." (PMID 38951492, 2024). "Interferon-induced transmembrane protein 3 (IFITM3) has been previously verified to be an endosomal protein that prevents viral infection." (PMID 38218875, 2024).
viral infection (continued). "Many of the genes corresponding to this factor such as IFI27, ISG15, IFITM3 are parts of the type 1 interferon signaling pathway normally observed in viral infections." (PMID 39369208, 2024). "Using these mouse models, IFITM3 was shown to prevent severe pathology upon virus infections in mice, including SARS-CoV-2, IAV (H1N1 and H3N2), WNV, CHIKV, Venezuelan equine encephalitis virus, RSV, and CMV." (PMID 38793616, 2024). "Apart from the viral infection studies, it was also noticed that heightened expression of the IFITM3 gene in the spleen and lungs of swine during an inflammatory response induced by lipopolysaccharide (LPS)." (PMID 39315180, 2024). "IFITM3 is concentrated in endo-lysosomal membranes since IFITM proteins are one of the host factors that restrict virus infection by impeding with cellular entry at endosomes." (PMID 38263024, 2024). "Other genes intimately involved in the host response to viral infection include the ICAM1 and IFITM3 genes that encode cell adhesion molecules." (PMID 37504295, 2023). "Here, we also aim to provide a mechanistic understanding of S-palmitoylation-regulated IFITM3’s trafficking in cells, membrane–sterol interactions, specificity, and activity against viral infections." (PMID 38140570, 2023). "Interferon-induced transmembrane protein 3 (IFITM3) is widely expressed in animal tissues, which serves as the first line of defense against virus infection." (PMID 37440496, 2023). "This significant upregulation of IFITM3 in platelets, driven by viral infection, indicates the implication of megakaryocytes and platelets to the antiviral response triggered by Omicron." (PMID 37828997, 2023). "Live cell trafficking studies of IFITM3 during virus infection led to a significant understanding of the mechanism of IFITM3 antiviral activity and the role of site-specific S-palmitoylation." (PMID 38140570, 2023). "The mechanism of EG against viral infection works by increasing IFITM3 expression, lysosomal protease activity, and lysosome acidification." (PMID 37239983, 2023). "Initially, it was suggested that IFITM3 blocks virus infection by disrupting cholesterol homeostasis in cells, leading to the accumulation of cholesterol in late endosomes and multivesicular bodies." (PMID 38140570, 2023). "For example, IFITM3 likely represents an increased resistance of these cells to viral infections, a property that has been observed in other SCs." (PMID 37652013, 2023). "The interferon-induced transmembrane-protein 3 (IFITM3) is a vital component of the immune system's defense against viral infection." (PMID 36403064, 2022). "IFITM3 mainly plays an antiviral role in the early stage of virus infection, and at least four antiviral mechanisms are suggested based on current studies." (PMID 35769480, 2022). "IFITM3 has been established as a therapeutic target against cancer and it has been shown to affect multiple viral infections including SARS-CoV2." (PMID 36153346, 2022). "IFITM proteins also play an important role in megakaryocytes, which regulate IFITM3 expression to activate antiviral immunity, and subsequent IFNα/β secretion also protects bystander hematopoietic stem cells from viral infection." (PMID 36466909, 2022). "IFITM3 was significantly upregulated (over 3-fold), and it plays a critical role in immunity during viral infection in that it directly engages and shuttles incoming virus particles to lysosomes." (PMID 35854219, 2022). "IFITM proteins (IFITM1, IFITM2 or IFITM3) have been shown to restrict multiple viral infections including influenza A virus West Nile virus and dengue virus." (PMID 36153346, 2022). "Using human TLR2 as a model, we show that IFITM3-Nogo-B interactions alter TLR dynamics post-viral exposure, highlighting a potential mechanism for IFITM3-Nogo-B regulation of the inflammatory response during viral infection." (PMID 36075894, 2022).